CDKN2A (cyclin dependent kinase inhibitor 2A)
Diseases named in the same sentence as CDKN2A in open-access papers (continued):
Sharing a sentence is not in itself a finding about the gene and the disease.
tumor (continued). "Our data attributes decreased regional mean diffusivity (MD) in NE tumor regions to co-occurrence of EGFR amplification and CDKN2A homozygous deletion, which reflects a high tumor cell density in these regions." (PMID 37770427, 2023). "Cdkn2a−/− tumour prone Lin− cells were first ex vivo transduced with a lentiviral vector expressing GFP under either spleen focus-forming virus (SFV) or PGK promoter/enhancer sequence." (PMID 37774002, 2023). "Variants in 5 genes (RPN1, CDKN2A, HRAS, PALB2, CBFA2T3) have been identified in 32 individuals with tumor from the extended cohort and classified as pathogenic, likely pathogenic, and VUS." (PMID 36845707, 2023). "Molecular CDKN2A status was determined using next-generation DNA sequencing, with homozygous CDKN2A deletion detected in 48% of the tumor cohort." (PMID 37138345, 2023). "Differential expression of the CDKN2A gene is evident in a variety of tumor tissues, with abnormal levels observed in tumor patients." (PMID 37876534, 2023). "This makes inactivation of the CDKN2A/RB1 pathway a major mechanism for grade 4 tumor development, at least with the treatment schemes used." (PMID 37932833, 2023). "Another commonly deleted key tumor suppressor gene is Cyclin Dependent Kinase Inhibitor 2A (CDKN2A)." (PMID 36741019, 2023). "The current study sought to investigate the expression status of CDKN2A in a panel of human tumors and study the possible correlation with tumor grade, stage, metastasis, and clinical outcome." (PMID 37626750, 2023). "CDKN2A (also known as p16) is a tumor suppressor gene and one of the most frequently deleted genes in cancer genomes." (PMID 37124062, 2023). "Although IDH status was not reported in the study, this population was likely enriched for IDH-wildtype tumours, and it was later shown that CDKN2A deletions lack prognostic impact in these tumours." (PMID 37504251, 2023). "CDKN2A expression in tumor tissues was significantly higher than normal tissues in GSE17025, GSE36389 and GSE11580 datasets." (PMID 37723477, 2023). "In this model, mice showed both intercranial and muscular tumour formation upon YT expression; an effect which was exasperated in Cdkn2a-null mice." (PMID 37296967, 2023). "The results showed that CDKN2A was mainly expressed in the malignant cells in tumor microenvironment, which indicated the important role of p16 in cancer cells." (PMID 36961395, 2023). "An integrated molecular grade based on TERT promoter and CDKN2A status was assigned for each tumor per the 2021 WHO Classification." (PMID 36723772, 2023). "In TCGA, one grade 4 tumor had both CDKN2A and RB1 called as homozygously deleted but only RB1 showed decreased expression." (PMID 37932833, 2023). "Only one tumor (1/9, 11%) demonstrated focal amplification of PDGFRA on chromosome 4q12, and only one tumor (1/9, 11%) demonstrated focal homozygous/biallelic deletion of CDKN2A and CDKN2B on chromosome 9p21." (PMID 38079020, 2023). "In CESC, the mean density of CDKN2A in tumor samples was higher than the corresponding normal tissue." (PMID 35813476, 2022). "On the other hand, activation of CDKN2A in keratinocytes seems to be related to tumor de-differentiation in head and neck areas." (PMID 36348437, 2022). "The tumor suppressor CDKN2A was significantly upregulated in the IL7RA-activated cells of the preleukemic mouse, as seen in the scRNAseq as well as in the bulk RNAseq." (PMID 35115489, 2022).
tumor (continued). "Half of the tumors (50%) carried at least one molecular alteration that is targetable in other tumor types, including alterations in CDKN2A (6.0% biallelically inactivated), ERBB2 (9.3%) and PIK3CA (10%)." (PMID 36335173, 2022). "Cox hazard proportion model showed that patients’ CDKN2A mutation in ctDNA (HR=16.1, 95% CI=4.4-59.1, P<0.001), ECOG score (HR=6.2, 95% CI=2.4-15.7, P<0.001) and tumor location (HR=0.4, 95% CI=0.1-0.9, P=0.027) were significantly associated with OS." (PMID 36081557, 2022). "The LC-BC CCPs formed have no more than 12 nodes and identified only seven genes (EDNRB, CDKN2A, VEGFD, FOS, GNG11, TGFBR2, and BIRC5) compromised in signaling pathways associated with the acquisition of tumor characteristics." (PMID 36101460, 2022). "We showed that CDKN2A/BHD is associated with poor prognosis in LUAD because of frequent co‐occurrence of IFN‐I functional loss, which leads to a suppressed tumor immune microenvironment." (PMID 35253368, 2022). "CDKN2A is one of the extensively studied tumor suppressor that plays a crucial role in cell cycle progression, differentiation, senescence, and apoptosis." (PMID 35056738, 2022). "Although various studies have classified CDKN2A as a tumor suppressor, some studies have identified its complex role in tumors." (PMID 35957699, 2022). "The anti-proliferative effect of Met-enkephalin (OGF) was most likely related to the activation of p16INK4a (also known as cyclin-dependent kinase inhibitor 2A, a known tumor suppressor) and p21WAF1/CIP1 (also known as cyclin-dependent kinase inhibitor 1)." (PMID 35456955, 2022). "In EAC patients, a significant association was found between CDKN2A, MGMT or TIMP3 promoter hypermethylation and tumor location (p = 0.034, p = 0.0070 and p = 0.013, respectively, Fisher’s exact test)." (PMID 35701814, 2022). "Cancerous squamous cell‐associated genes such KRT5, CDKN2A, and SERPINB3 were mainly enriched in the Stereo‐seq tumor areas, IGKC and IGLC2 were enriched in inflammatory areas, VIM in stromal areas, ADRA2A in blood vessels, and MUC5B in glands." (PMID 35986392, 2022). "Cyclin-dependent kinase inhibitor 2A (CDKN2A), a cyclin-dependent kinase inhibitor gene, that encodes the p16 protein involved in the regulation of cell cycle pathways, is known as a tumor suppressor." (PMID 36052076, 2022). "The aim of this study was to examine the possible association between CDKN2A, MDM2, E2F2 and LTF mRNA expression in the OSCC tumour and margin samples and influence on clinical variables in the Caucasian Polish population." (PMID 36551770, 2022). "These include methylation patterns, copy number alterations, and mutually exclusive driver mutations affecting oncogenes, including BAP1, CDKN2A/B, and the TERT promoter, which are associated with particularly aggressive tumor biology." (PMID 35299730, 2022).
tumor (continued). "Firstly, CDKN2A/p16 is a tumor suppressor gene locus that lies adjacent to the 9p21.3 genomic region, which is the site of loss of heterozygosity in some malignant tumors." (PMID 35396552, 2022). "CDKN2A is an established tumor suppressor gene with roles in angiogenesis, cell death, invasiveness, and growth suppression." (PMID 35538064, 2022). "CDKN2A is a prognostic biomarker that is associated with immune infiltration in HCC, and its expression can contribute to the regulation of tumor-associated macrophages." (PMID 36588699, 2022). "In particular, the CDKN2A/p16INK4a/CDK4-6/RB pathway is a well-known cascade involved in tumor cell proliferation across multiple cancer types." (PMID 36248987, 2022). "Compared to mosaically introduced RasG12V cells in normal skin, those in doxorubicin-treated skin relatively strongly expressed cdkn2a/b, il1b, 1l11b, and ROS and efficiently induced tumour-like cell masses." (PMID 35304872, 2022). "Underscoring the complexity of DMG biology, residual PRC2 activity has been shown to be essential for tumor growth through H3K27me3 retention and subsequent transcriptional repression of critical tumor suppressors such as CDKN2A." (PMID 36589742, 2022). "As expected, somatic disruption of the known senescence cell cycle regulator and potent tumor suppressor, Cdkn2a, also resulted in increased tumor burden." (PMID 35017504, 2022). "Further analysis demonstrated a significant correlation between CDKN2A and pTNM stage, tumor grade, immune cell infiltration, drug sensitivity, tumor mutational burden (TMB) score, and microsatellite instable (MSI) score." (PMID 35937995, 2022). "CDKN2A was reported to be a tumor suppressor gene on chromosome 9p21.3 that played a role in tumor suppression of tumor proliferation." (PMID 35790864, 2022). "To further explore the molecular characteristics of CDKN2A in BRCA, we performed the relationship between CDKN2A and tumor-infiltrating immune cells using the CIBERSORT algorithm." (PMID 36052076, 2022). "Regarding 15L and 17L, we observed an increment in CDKN2A CN log ratio (from −4.2 to −0.4) along with the restoration of p16 expression, suggesting that selection of tumor cells retaining normal CDKN2A CN was favored upon treatment." (PMID 36071033, 2022). "Along with high KRAS mutation rates and RAS84 expression, RAG-1 was characterised by STK11/LKB1 mutations (KL tumours) and RAG-4 by CDKN2A mutations (KC tumours)." (PMID 36163168, 2022). "Subsequent analyses depicting hallmarks of tumor microenvironment (TME) among three subtypes suggested strong association between TNBC and CDKN2A." (PMID 36052076, 2022). "The results showed that only CDKN2A was upregulated and the other 9 CRGs were downregulated in tumor tissues." (PMID 36536785, 2022). "The result shows that CDKN2A mainly acts from the perspective of tumor cells while the remaining genes mainly act by regulating the immune response." (PMID 36581816, 2022).
tumor (continued). "At the same time, we also detected Ki67 and PCNA, which were related to tumor proliferation, and the results showed that the protein level of CDKN2A in OS tissues was positively correlated with ki67." (PMID 36263140, 2022). "Two of the 4 unrelated patients had CDKN2A c.71G>C mutation and both exhibited LOH on the tumor sample testing." (PMID 35123577, 2022). "Similar to our study, it has reported that CDKN2A are related to the immune response and tumor immune microenvironment in tumors." (PMID 36246586, 2022). "Biologically, CDKN2A in tumor cells halts progression of the cell proliferation cycle at the G1 phase." (PMID 36380219, 2022). "Our data suggests that myeloid-high, stroma-enriched, neoantigen-depleted tumor regions historically experienced a cytotoxic T cell response, which prompted the selection of tumor clones losing neoantigens and/or HLA/CDKN2A/B." (PMID 36536472, 2022). "High expression of cyclin dependent kinase inhibitor 2 A (CDKN2A) was associated with good overall survival, consistently with its function as a tumor suppressor." (PMID 36309506, 2022). "Previous sequencing studies of human Spitz melanomas have made similar observations, i.e. that inactivation of tumor suppressors, such as CDKN2A, frequently occur in Spitz melanomas." (PMID 36017742, 2022). "In the present study, we analyzed the DNA methylation levels of CDKN2A, which is a tumor suppressor gene, and widely modified in a range of cancers." (PMID 34854470, 2022). "Acquisition of mutations, mainly affecting KRAS or tumor suppression genes (e.g., TP52, CDKN2A, and SMAD4), accelerates development of pancreatic ductal adenocarcinoma." (PMID 36421339, 2022). "In particular, the cell cycle regulator P16 (or CDKN2A) is believed to play a crucial role in mediating cellular senescence and preventing tumour growth." (PMID 36170022, 2022). "CDKN2A (also known as P14ARF or P16INK4A) is a G1-S cell cycle regulator and tumor repressor, the loss-of-function mutations and epigenetic inactivation of which have been observed in various cancer types, including HCC." (PMID 36563143, 2022). "In SCC, genes that are commonly hypermethylated to repress their expression and tumor-suppressive activities include CDKN2A and RASSF1 (growth arrest), MGMT (DNA repair), and DAPK (apoptosis)." (PMID 35912167, 2022). "As a result, HDAC participates in p16INK4 hypermethylation (cyclin-dependent kinase inhibitor 2A), which coordinates with the E2F factor to inactivate tumor suppressor genes." (PMID 35847783, 2022).
tumor (continued). "Cell cycle-related genes, including CCND1, CDK4, CDKN2A, and RB1, were frequently mutated in MSCs, PCs, and tumor cells." (PMID 35087207, 2022). "p16INK4A and p15INK4B, encoded by CDKN2A and CDKN2B, respectively, play significant roles as tumor suppressors in the INK4 family." (PMID 35892870, 2022). "Of the four putative tumor suppressors, CSMD3 has a disputed cancer role and a likely inflated mutation rate, while CDKN2B cooperates with its paralog CDKN2A to inhibit cell cycle, supporting its tumor suppressor role." (PMID 35078504, 2022). "Here, we report that there are CDRs in many tumor suppressor genes, such as CDKN2A, miR31HG, PTEN, and RB1, which are commonly inactivated by SCND in various human cancers." (PMID 36531022, 2022). "CDKN2A is a tumor suppressor gene located on the chromosomal region 9p21 along with CDKN2B and Methylthioadenosine phosphorylase (MTAP) gene." (PMID 36362209, 2022). "Inactivation of cell cycle control (through CDKN2A alterations for example) would allow tumor cells to escape from TGFβ-mediated suppressive effects." (PMID 35982973, 2022). "Genetic analyses of human PDAC indicate that CDKN2A deletions are an early event in tumor evolution." (PMID 36344707, 2022). "Common tumor suppressors silenced in NPC and EBV-associated gastric cancer include: RASSF1, CDKN2A/p16, CDH1, and PTEN." (PMID 36560704, 2022). "Specifically, in DMG where 80% of cases express the mutant H3K27M histone, focal gains of the H3K27me3 mark on critical tumor suppressors such as Cdkn2a among others have been implied as an indirect consequence of residual EZH2 activity." (PMID 35395831, 2022). "Among 31,600 tumor samples (12,051 with PD-L1 IHC), 5103 (16%) were CDKN2A del+ and 26,497 (84%) were CDKN2A del−." (PMID 35739333, 2022). "The correlation between the expression of cell cycle-related genes and immune cells suggested roles for CDK4, CCNB1, CHEK1 and CDKN2A in regulating HCC tumor immunology." (PMID 36403263, 2022). "After 5 weeks of injection, the tumor volume and weight of the CDKN2A knockdown group were significantly reduced compared to those of the control group." (PMID 36581816, 2022). "For example, the chr9p21 is the most frequent deleted region in cancer genomes, which contains the important tumor suppressors such as CDKN2A (p16), CDKN2B (p15)." (PMID 35244719, 2022). "The expression patterns of PLK1 and CDKN2A were considerably up-modulated in most tumour types, while KLF9 was the opposite." (PMID 36186436, 2022). "Eight genes were significantly downregulated in tumor samples, and only CDKN2A was significantly overexpressed." (PMID 36212436, 2022). "The presence of well-known mutations reported in genes that commonly occur in EAC, known as driver mutations like ARID1A, CDKN2A, KRAS, APC, SMAD4, and PI3KCA, and a high tumor mutation burden (TMB) level makes EAC a highly heterogeneous disease." (PMID 35328735, 2022). "The MTAP/CDKN2A locus encompasses two functional tumour suppressor genes, CDKN2A and CDKN2B, that are known to play a role in familial and sporadic melanoma risk, as well as a number of other genes with potential involvement in this disease." (PMID 35357426, 2022). "After overexpression of CDKN2A, the capacities of cell proliferation, colony formation and tumor sphere formation came back to control level." (PMID 35042525, 2022). "The most prominent homozygous deletions in cancer affect chromosome 9p21.3 and eliminate CDKN2A/B tumor suppressors, disabling a cell-intrinsic barrier to tumorigenesis." (PMID 36344707, 2022).